DICER1 (dicer 1, ribonuclease III)
Diseases named in the same sentence as DICER1 in open-access papers (continued):
Sharing a sentence is not in itself a finding about the gene and the disease.
adenoma (12 papers, 2013 to 2025). A neoplasm arising from the epithelium. "The additional study of one of the macrofollicular adenomas confirmed the constitutional DICER1 c.4068_4069delGT, p(Tyr1357fs*18) variant, along with two somatic DICER1 variants c.5126A > G, p.(Asp1709Gly) (VAF: 19%) and c.5429A > T, p.(Asp1810Val) (VAF: 11%)." (PMID 40892116, 2025). "Corticotrophin tumor/adenoma in association with primary intracranial sarcoma, DICER1‐mutant." (PMID 40040389, 2025). "Consequently, the final diagnosis of “corticotroph tumor/adenoma associated with primary intracranial sarcoma, DICER1‐mutant” was made after confirming the presence of DICER1 mutations." (PMID 40040389, 2025). "Conversely, in DICER1-driven tumors, DICER1 mRNA levels were reported to be increased, with higher levels in carcinomas than in adenomas." (PMID 40448797, 2025). "A strong DICER1 expression was demonstrated in 32% of adenomas and in 51% of carcinomas (p = 0.028)." (PMID 26087193, 2015). "In order to investigate the reason for the higher frequency o DICER1 overexpression in ACCs than in adenomas, we evaluated the expression of miR-103 and miR-107 in adrenocortical adenomas and ACCs." (PMID 26087193, 2015). "In this study, we assessed DICER1 e TRBP protein expression in 154 adult adrenocortical tumors (75 adenomas and 79 carcinomas)." (PMID 26087193, 2015). "The median score for DICER1 immunoreactivity was 2.2 (range, from 0 to 6) and 3.5 (0 to 7) for adenomas and ACCs respectively (p = 0.001)." (PMID 26087193, 2015). "DICER1 mRNA levels were significantly higher in ACCs (median 3.9, range from 0.37 to 21.3) than in adenomas (1.7, from 0.36 to 23.33; p = 0.015)." (PMID 26087193, 2015). "In the currenty study, we demonstrated that DICER1 expression was higher in ACCs when compared to adenomas in adults." (PMID 26087193, 2015). "In adult ACTs, a strong DICER1 expression was found in 24 out of 75 adenomas (32%) and in 39 out of 79 ACCs (49%; X2 = 4.8, p = 0.028)." (PMID 26087193, 2015). "Similarly, DICER1 gene overexpression was more frequent in ACCs (60%, 15 out of 25) than in adenomas (23%, 7 out of 30; X2 = 7.64, p = 0.006)." (PMID 26087193, 2015). "Similarly, DICER1 gene overexpression was more frequent in carcinomas (60%) than in adenomas (23%, p = 0.006)." (PMID 26087193, 2015). "Based on our findings, we can speculate that DICER1 overexpression at mRNA and protein levels in ACCs compared to adenomas can represent a compensatory event due to deregulation of miRNA machinery components in malignant tumors." (PMID 26087193, 2015). "In conclusion, DICER1 gene and protein expression was higher in ACCs than in adenomas." (PMID 26087193, 2015). "Here, we evaluated the mRNA expression of DROSHA, DGCR8, DICER (DICER1), TARBP2, and PRKRA, the core components in the miRNA biogenesis pathway, in a cohort of 73 adrenocortical tumors (including 43 adenomas and 30 carcinomas) and nine normal adrenal cortices using a RT-qPCR approach." (PMID 23671264, 2013).
myelodysplastic syndrome (12 papers, 2014 to 2025). A clonal hematopoietic disorder characterized by dysplasia and ineffective hematopoiesis in one or more of the hematopoietic cell lines. "Here, we analyze 3′-UTR variants in DICER1 and DROSHA genes in the context of myelodysplastic syndrome (MDS) development." (PMID 34287278, 2021). "Our previous study showed that Dicer1 expression is reduced in MSCs from myelodysplastic syndrome patients (MDS) and that this down-regulation promotes cellular senescence and decreases the stem cell-supporting capacity of these cells." (PMID 29724992, 2018). "Experiments using mice have reported an association between genetic mutations, such as Dicer1 in MSCs, but not in HSCs, resulting in myelodysplastic neoplasms." (PMID 41463596, 2025). "Moreover, the deletion of Dicer1 in mouse osteo-lineage cells in a specific hematopoietic niche can result in myelodysplasia; mice with this alteration eventually develop myelodysplastic syndrome (MDS) and secondary leukemia." (PMID 25366136, 2014). "Deletion of Dicer1 in osteoprogenitors has been shown to result in myelodysplastic syndrome (MDS) with sporadic transformation to AML." (PMID 34206957, 2021). "If it is possible to induce specific genetic abnormalities such as DICER1 in UE7T-9, it is expected that a human–mouse hybrid bone marrow niche can be reproduced in mice, leading to the creation of a myelodysplastic neoplasm model and a more detailed analysis." (PMID 41463596, 2025). "In particular, the downregulated expression of both miRNA processing endonucleases, DICER1 and DROSHA, was demonstrated in MSCs from myelodysplastic syndrome patients compared to normal cells." (PMID 34572006, 2021). "Importantly, decreased expression of Dicer1 was detected in MSC-derived osteoprogenitors from myelodysplastic syndrome (MDS) patients, along with a reduction of the SBDS gene." (PMID 31861268, 2019). "Moreover, further investigations demonstrated the downregulated expression of both miRNA processing endonucleases DICER1 and DROSHA in MSCs from myelodysplastic syndrome patient cells compared to normal cells." (PMID 34287278, 2021). "Examples include the deletion of Dicer1 in osteoprogenitors, which leads to the development of myelodysplastic syndrome (MDS) with sporadic transformation to AML, or overexpression of β-catenin in osteoblasts as observed in 38% of the patients diagnosed with MDS or AML." (PMID 36742324, 2023).
embryonal tumor (11 papers, 2019 to 2025). "In embryonal tumor with multilayered rosettes, a rare but aggressive brain tumor, DICER1 mutations are frequently observed." (PMID 40666073, 2025). "Embryonal tumour with multilayered rosettes (ETMR) is another type of common aggressive embryonal tumour in young children, with C19MC-altered or DICER1-altered molecular signatures." (PMID 37370764, 2023). "None harbored DICER1 mutation or amplification of the chromosome 19 microRNA cluster (C19MC), thereby distinguishing these tumors from embryonal tumor with multilayered rosettes." (PMID 36437415, 2023).
gastric cancer (11 papers, 2015 to 2025). A primary or metastatic malignant neoplasm involving the stomach. "For example, SNVs in DROSHA have been associated with gastric cancer and susceptibility to congenital heart disease, whereas gene variants in DICER1 occur at significantly higher allele frequencies in individuals with endometrial and hepatocellular carcinoma than in the healthy population." (PMID 36968598, 2023). "In gastric cancer, a low DICER1 staining was a predictor of local linfonodal invasion." (PMID 26087193, 2015). "However, miR-192 serves as a poor prognosis marker in other cancer types including neuroblastoma targeting Dicer1, gastric cancer targeting RAB11-FIP2 and SMG-1, NSCLC targeting the FGFR3/RB1 pathway, hepatocellular carcinoma targeting SEMA3A, and pancreatic cancer targeting SIP1." (PMID 33614788, 2021). "This potential contrasts with its oncogenic role in gastric cancer via targeting Dicer 1, Ribonuclease III (DICER1) and Phosphatase and TENsin homolog (PTEN) highlighting tissue-specific functionality." (PMID 41215804, 2025). "miR-107 acts as an oncogene and regulates gastric cancer development and progression by targeting NF1, DICER1, FOXO1, and CDK825,27,28,41." (PMID 30258124, 2018).
hepatocellular carcinoma (11 papers, 2016 to 2024). A malignant tumor that arises from hepatocytes. "Knockdown of Dicer1 in hepatoma Hepa1–6 cells promoted transplanted tumor formation by these cells in isogenic C57BL/6 mice." (PMID 33658044, 2021). "Moreover, the hnRNP D reduces the Dicer1 levels by targeting the 3′-UTR of DICER1 mRNA, causing down-regulation of tumor suppressor miR-122 and increased viability of PLC/PRF/5 hepatoma as well as Huh7 liver derived cell lines." (PMID 32596243, 2020). "Based on above data that AUF1 can modulate the expression of miR-122 by targeting DICER1 mRNA, we further evaluated whether other miRNAs could be affected by AUF1 in hepatoma cells." (PMID 29599909, 2018).
Leydig cell tumor (11 papers, 2013 to 2025). A sex cord-stromal tumor occurring in the testis and rarely in the ovary. "In one series, 60% of the Sertoli-Leydig cell tumors was found to have DICER1 mutation, and some occurred in the setting of germline DICER1 mutation." (PMID 38352891, 2024). "Sertoli–Leydig cell tumors of moderate and poor differentiation exhibit a high association with DICER1 syndrome, which is characterized by germline mutations of the DICER1 gene." (PMID 37508611, 2023). "It is recommended to perform germline DICER1 mutation testing in all patients with Sertoli–Leydig cell tumor since a positive result is important for follow-up and genetic counseling." (PMID 37508611, 2023). "Another study confirmed this, indicating that more than 60% of ovarian Sertoli–Leydig cell tumors diagnosed harbored DICER1 mutations within the RNase III domains." (PMID 29762508, 2018). "Ovarian sex cord-stromal tumors have been associated with DICER1 mutations, specifically, ovarian Sertoli–Leydig cell tumors." (PMID 29762508, 2018). "It was recently shown that hot-spot DICER1 mutations were highly prevalent in Sertoli–Leydig cell tumors." (PMID 26087193, 2015). "Since Sertoli–Leydig cell tumors are steroidogenic tumors, it prompted us to investigate DICER1 hot-spot mutations in ACTs." (PMID 26087193, 2015). "Moreover, Sertoli–Leydig cell tumors are known to have an association with the DICER1 gene and can be part of the clinical spectrum of DICER1 syndrome." (PMID 39336518, 2024). "Articles were identified via National Center for Biotechnology Information (NCBI) PubMed literature database using the search terms “DICER1 germline mutations and ovarian Sertoli–Leydig Cell Tumor” or “DICER1 germline variants and ovarian Sertoli–Leydig Cell Tumor”." (PMID 33922805, 2021). "However, in contrast to the situation with PPB, the penetrance of Sertoli–Leydig cell tumors in MNG patients with DICER1 mutations appears to be much higher." (PMID 23641362, 2013). "In contrast to the germline mutations in DICER1 reported in PPB and MNG, the somatic DICER1 mutational “hot-spots” identified in Sertoli–Leydig cell tumors are located at metal-binding sites critical for miRNA interaction and cleavage within the RNase IIIb domain of this gene product." (PMID 23641362, 2013). "Retiform pattern, i.e., a growth pattern resembling rete ovarii/rete testis, is a sex cord-like pattern which can be found Sertoli–Leydig cell tumors, especially in DICER1-mutant cases (which tend to be more aggressive than DICER1-wild-type cases)." (PMID 40150134, 2025). "Similar mechanisms could contribute to the pathogenesis of Sertoli–Leydig cell tumors or other categories of pediatric sex-cord-stromal tumors where germline or somatic DICER1 mutations have not been observed." (PMID 23641362, 2013).
tumor predisposition syndrome (11 papers, 2014 to 2025). "The DICER1 gene, essential for microRNA biogenesis and posttranscriptional gene regulation, has been implicated in a variety of benign and malignant neoplasms, particularly within the context of the DICER1-related tumor predisposition syndrome." (PMID 41335141, 2025). "DICER1 tumor predisposition syndrome (DTPS) is a genetic disorder that predisposes affected individuals to a wide range of tumors that have mainly pediatric onset." (PMID 37333613, 2023). "DICER1 syndrome is a tumor predisposition syndrome caused by abnormal micro-RNA processing which leads to a variety of benign and malignant neoplasms in many organ systems, including the central nervous system." (PMID 37508972, 2023). "List of germline DICER1 missense variants in persons with DICER1 tumor predisposition syndrome (DTPS)." (PMID 37333613, 2023). "Germline pathogenic variants (GPVs) in DICER1 result in DICER1 tumor predisposition syndrome (DTPS), a mainly childhood-onset tumor susceptibility disorder." (PMID 37333613, 2023). "Carriers of the DICER1 germline mutation have been found to be at risk for pleiotropic tumor predisposition syndrome." (PMID 26241669, 2015). "Currently, there is no indication of DICER1 tumor predisposition syndrome in this case; however, continued monitoring and follow‐up are warranted." (PMID 40040389, 2025). "The gastrointestinal system is the site of involvement by several syndromes and DICER1 tumor predisposition syndrome is no exception." (PMID 34599283, 2022).
adenosarcoma (10 papers, 2017 to 2025). A low grade malignant neoplasm characterized by the presence of a benign epithelial component (tubular and cleft-like glands) and a low grade sarcomatous component that contains varying amounts of fibrous and smooth muscle tissues. "Sanger sequencing was employed to screen for somatic Hotspot mutations in the RNase IIIb domain of DICER1 in the 22 adenosarcomas." (PMID 38570882, 2024). "In this study, we conducted an analysis of the clinicopathological characteristics of 22 adenosarcomas, with a particular focus on screening for DICER1 hot mutations." (PMID 38570882, 2024). "In summary, our study of 22 Müllerian adenosarcomas focused on the clinicopathological features and the presence of DICER1 Hotspot mutations." (PMID 38570882, 2024). "In conclusion, our study provides a detailed examination of the clinical, pathological, and genetic characteristics of Müllerian adenosarcomas, with a specific focus on DICER1 Hotspot mutations." (PMID 38570882, 2024). "Adenosarcomas have been found to exhibit DICER1 mutations in approximately 20% of cases, primarily as somatic mutations." (PMID 38570882, 2024). "A very recent report highlighted the importance of a Dicer1 mutation in anaplastic sarcomas of the kidney, and other recent publications have shown that Müllerian adenosarcoma tumorigenesis is characterized by a somatic Dicer1 mutation." (PMID 34722255, 2021). "Furthermore, in a targeted genomic analysis of adenosarcoma, two out of 18 tumors were found to have DICER1 mutations." (PMID 38570882, 2024). "However, it should be noted that DICER1 mutations have been primarily reported in a small subset of adenosarcomas with rhabdomyosarcomatous elements, but this alteration is not exclusively associated with heterologous rhabdomyosarcomatous differentiation." (PMID 38570882, 2024). "Furthermore, there is a case report documenting the presence of germline DICER1 mutation in adenosarcoma." (PMID 38570882, 2024). "The presence of DICER1 mutation was observed in 2 out of 9 cases of high-grade adenosarcoma, while no mutation was detected in low-grade adenosarcoma." (PMID 38570882, 2024). "In our study, we conducted screening for RNase IIIb Hotspot mutation sites in adenosarcoma tumors and found no DICER1 mutations." (PMID 38570882, 2024). "While we did not identify any DICER1 Hotspot mutations in our cohort, these findings contribute to our understanding of the genetic heterogeneity of adenosarcomas." (PMID 38570882, 2024). "Several cancer genes rarely mutated in adenosarcomas, such as DICER1 (11%), FGFR2 (11%), and BRCA2 (5%), were not mutated in any of the PTs analyzed." (PMID 28267263, 2017). "On the other hand, since DICER1 mutations are present in 26% to 42% of adenosarcomas, the presence of DICER1 mutations does not differentiate ERMS from adenosarcoma." (PMID 40161378, 2025).
blastoma (10 papers, 2014 to 2025). A malignant neoplasm composed of undifferentiated cells. "Evaluation for DICER1 mutations should be performed if there is a family history of this syndrome, the lung cyst/neoplasm is a pleuropulmonary blastoma, or other clinical manifestations of this syndrome are present or develop." (PMID 33363744, 2020). "Given that “blastoma” is a well-accepted terminology in the spectrum of DICER1-associated malignancies, the term “thyroblastoma” might be more convenient for these malignant teratoid tumors of the thyroid gland." (PMID 32507920, 2020). "Moreover, with respect to DICER1 related cancers, several studies have suggested that loss of function or mutation of DICER1 may affect stem cell proliferation, differentiation, and cell fate and induce embryonal or blastoma carcinomas." (PMID 30833603, 2019).
follicular thyroid carcinoma (10 papers, 2020 to 2026). "A minimally invasive follicular thyroid carcinoma with a solid and microglandular growth pattern along with numerous mitotic figures was described in an 18-year-old female with a germline DICER1 variant." (PMID 40448797, 2025). "In the adult population, RAS is the predominant mutation found in FTC and the follicular variant PTC (FVPTC) whereas DICER1 mutations are found in only 5–8% of follicular adenomas and follicular thyroid carcinomas." (PMID 38254836, 2024). "The second condition is macrofollicular-predominant follicular thyroid carcinomas in any age group where 75% (six out of eight) of these neoplasms were shown to have DICER1 mutations along with an additional mutation in most cases." (PMID 38254836, 2024). "In the thyroid gland, during childhood or adolescence, DICER1-driven tumors include differentiated follicular thyroid carcinoma and, more rarely, poorly differentiated carcinoma." (PMID 40448797, 2025). "In 27 VUS carriers, there was one woman in her 20s (germline p.Asn1393_Thr1394insAsn) with a follicular thyroid carcinoma; on somatic sequencing, no DICER1 hotspot variant was detected." (PMID 33630087, 2021). "DICER1 mutations have been reported in subsets of follicular thyroid carcinoma (FTC), but the role of DICER1 in follicular thyroid tumorigenesis has not been extensively studied." (PMID 32163919, 2020).